TGFBR1 (transforming growth factor beta receptor 1)
Diseases named in the same sentence as TGFBR1 in open-access papers (continued):
Sharing a sentence is not in itself a finding about the gene and the disease.
tumor (continued). "In addition, the migration effects of PL on tumor cells were attenuated after TGFBR1 overexpression." (PMID 33413277, 2021). "Interestingly, these tumours induced the over-production of TGFβ in the CAFs and treatment with galunisertib, the TGFBR1 specific inhibitor to block CAF: TGFβ responses, reduced tumour growth, and metastasis." (PMID 33669775, 2021). "Importantly, the aggressive top-down tumours that emerge, following Tgfbr1 deletion, exhibit deregulated MAPK signalling and are therefore sensitive to MEK1/2 inhibition, providing an opportunity for early therapeutic intervention." (PMID 33673710, 2021). "In PTC, SLC35F2 expedites the proliferation and migration of tumor cells by targeting TGFBR1." (PMID 34335744, 2021). "In this context, TGF-beta pathway blockade through TGF-beta receptor (TGFBR)-1 inhibition or TGF-beta blocking antibody enabled T cells infiltration into the tumor, restoring the anti-tumor immunity induced by the anti-PD-L1 antibody in BC and CRC pre-clinical models." (PMID 33553157, 2020). "TGBβ, highly secreted by the KIR2DL2/L3/S2+ CD8+ T cells, which in turn also over-expressed the TGFBR1, could have further sustained tumor evasion by promoting an immune-suppressive tumor microenvironment." (PMID 33076479, 2020). "TGFBR-1 inhibitor (galunisertib) and anti-PD-L1 combination treatment increased intra-tumoral T cell infiltration and activation, thereby promoting a potent anti-tumor response in CRC and BC pre-clinical models." (PMID 33553157, 2020). "It is tempting to speculate that the TGFBR1 mutations in MSSE have a reciprocal effect, promoting the early stages of tumor development." (PMID 33256177, 2020). "We found that TGFBR1 was significantly overexpressed in tumour tissues." (PMID 32076068, 2020). "Moreover, suppression of PTEN in concert with other tumour suppressors, like transforming growth factor beta-receptor 1 (TGFBR1), can also contribute to deregulated PI3K-mTOR signalling." (PMID 30970654, 2019). "Additionally, they found that TGFBR1 inhibition prevents metastasis but promotes the expansion of tumor-initiating cells." (PMID 31257133, 2019). "Oncogene activation by the conditional knockout of Pten and Tgfbr1 may contribute to the tumour‐immunosuppressive microenvironment with concomitantly significant increase in MDSCs and TAMs." (PMID 28401653, 2017). "Among them are cancer-related genes such as MYB and TGFBR1 as well as many immune-related genes such as CCR7 and FCRL3, whose prognostic association is likely to reflect the inflammatory process and the presence of lymphocytic cells in the tumour." (PMID 28059167, 2017). "Consistent with the tumorigenic effect, overactivation of TGFBR1 altered tumor microenvironment by promoting angiogenesis and enhanced ovarian cell proliferation, accompanied by impaired cell differentiation and dysregulated expression of critical genes in ovarian function." (PMID 27344183, 2016). "qRT–PCR analysis of these tumours revealed loss of Tgfbr1 expression without any significant change in ligand mRNA expression." (PMID 27558455, 2016). "In addition, we found that the expression levels of Nras and Tgfbr1 were significantly elevated in both normal tissue adjacent to the tumor and in the opposite hemisphere regions in the oligomer-treated group compared with the saline-administered control." (PMID 27102443, 2016). "Thus, it is conceivable that activation of AKT, as a direct or indirect consequence of TGFβ signaling activation, accelerates tumor progression in the TGFBR1-CAAcre mice." (PMID 27344183, 2016).
tumor (continued). "Indeed, our murine and zebrafish xenograft models show that targeting autocrine TGFβ secretion and TGFBR1 kinase activity inhibits xenograft tumour establishment in mice and prevents metastatic spread in zebrafish tissues." (PMID 27835901, 2016). "To investigate further the potential for TGFBR1 inhibitors to prevent vemurafenib resistance, we tested both in vitro derived resistant lines (A375R), and patient derived vemurafenib-resistant recurrent tumour cells for sensitivity to SB-431542 (10μM)." (PMID 27835901, 2016). "In blood of tumor bearing Tgfbr1/Pten 2cKO mice, PD-1 blockade increased MHC-II+ and CD40+cells." (PMID 26573233, 2015). "TGFBR1*6A genotypes were the same as observed with blood samples (data not shown), with no loss of homozygosity of TGFBR1 in the tumor samples." (PMID 20429896, 2010). "In addition to this altered copy of TGFBR1, the tumour still had at least one normal coding sequence of the gene." (PMID 19643034, 2009). "The pivotal role TGFBR1 plays in tumour development makes the hypothesis that germ-line variation in the gene may influence CRC susceptibility an attractive concept." (PMID 19401691, 2009). "At least one normal coding sequence of TGFBR1 was also present in the tumour ME." (PMID 19643034, 2009). "Similarly, TGFBR1 expression was enhanced in tumor tissues from PC patients." (PMID 39425009, 2024). "Thus, the tumor-fibroblast crosstalk may promote tumor angiogenesis by activating the TGFBR1-SMAD signaling pathway, which, in turn, stimulates deposition of fibronectin fibrils promoting the endothelium-pericyte association." (PMID 29921235, 2018). "To further elucidate the underlying mechanism of miR-769-5p on the development of NSCLC, we conducted an in vitro study using NSCLC cell lines and showed that direct targeting of TGFBR1 protein expression may mediate the tumor-suppressing function of miR-769-5p." (PMID 29371929, 2017). "Subsequent functional analysis of four TGFBR1 mutants and five TGFBR2 mutants indicated that half of the TGFBR1 mutants and all five TGFBR2 mutants were loss of function for canonical Smad signalling, and that tumours harbouring TGFβ receptor mutations had reduced PO4-SMAD3 activity." (PMID 27558455, 2016). "Non-coding RNA could suppress tumor growth and metastasis by targeting TGFBR1 in HCC." (PMID 25476897, 2014). "TGF-β exerted its tumor-suppressor effects on many tumors by binding to the transmembrane TGF-β type II receptor (TGFBR2, a tumor suppressor), which caused the recruitment of the TGF-β type I receptor (TGFBR1) with subsequent activation of the receptor complex." (PMID 18570662, 2008). "Functionally, miR-490-3p acts as a tumor suppressor, inhibiting migration and EMT by directly targeting the upstream receptor TGFBR1 and the downstream transcription factor TGIF2 within the TGF-β signaling pathway." (PMID 40565099, 2025). "Both tumor cells and infiltrating macrophages secrete high levels of transforming growth factor-β (TGF-β), which bind TGFBR1/2 and triggers phosphorylation of Smad2/3." (PMID 40958866, 2025). "Tumor cells exhibited strong interactions with CAFs, primarily involving TGFB1/2 (Tumor) - TGFBR1/2 (CAF) and various collagen-integrin pairs, particularly enriched in MIP and ACI regions." (PMID 40918135, 2025). "It appears that tumor development is unaffected by constitutional heterozygous loss-of-function TGFBR1 mutations, indicating that the majority of cells with a single functioning copy of the TGFBR1 gene have not experienced significant disruptions in TGFβ signaling." (PMID 40612107, 2025). "In this context, miRNAs inhibiting expression of PTEN (miR-425 and miR-148a) should be considered as oncomirs, and those inhibiting KRAS, EGFR, PIK3CA, TGFBR1, and SMAD2 (let-7g, miR-150, miR-128, miR-139, miR-148a, miR-148b) as tumor suppressors." (PMID 40868120, 2025).
tumor (continued). "For TGFB1 and the receptors TGFBR1 and TGFBR2, a higher expression was detectable in tumor tissue compared to vestibular nerve tissue, which is congruent with the CSF data." (PMID 39272860, 2024). "TGFbR1 overexpression mediated by circEHBP1 activates the TGF-b/SMAD3 signalling pathway, promoting VEGF-D secretion; this leads to tumour lymphangiogenesis and the lymphatic spreading of bladder cancer cells." (PMID 38203852, 2024). "In the present study, we revealed a novel feedback loop between HCC tumor cells and fibroblasts mediated by the SPP1-CD44 and CCN2/TGF-β-TGFBR1 interaction pairs." (PMID 39095854, 2024). "We searched public databases for TGFBR1 and TGFBR2 gene expression in tumor-infiltrating immune cells." (PMID 38441961, 2024). "Our results revealed a high interaction potential between TGFβ secreted from immune cells and TGFBR1 and TGFBR2 in tumour cells." (PMID 38426403, 2024). "We uncovered a positive loop between tumor cells and fibroblasts mediated by SPP1-CD44 and CCN2/TGF-β-TGFBR1 interaction pairs." (PMID 39095854, 2024). "Our results indicate that AV25R binds with several proteins known to regulate cell proliferation and tumor progression, such as FECH, MAP11, EGFR, TGFBR1 and MDM2." (PMID 38138609, 2023). "A tendency towards the upregulation of several known suppressors of anti-tumor immunity and initiators of epithelial-mesenchymal transition (EMT) was observed: TGFBR1, TGFBR2, TGFB3 and TPT1." (PMID 37033948, 2023). "Next, correlation of TGFBR1 and expression of the miRs were evaluated in twenty pairs of surgically resected HCC tissues and corresponding non-tumor tissues from the Ajou University Hospital (Suwon, South Korea)." (PMID 36901700, 2023). "To determine the impact of TGFBR1 overactivation on cell identify, we performed immunostaining of SOX9 using testes from 1-month-old mice prior to gross tumor formation." (PMID 38067144, 2023). "Activin type 1 or TGFBR1 phosphorylates it, subsequently recruits SMAD4 and transmits signals to the nucleus, and is thought to suppress tumor development." (PMID 37509254, 2023). "The probability of interaction between tumor cells and fibroblast receptor-ligand pairs was higher than that of thyroid cells, especially in TGFB1/ACVR1/TGFBR1, FGF18/FGFR1, BTC/EGFR, BMP8A/BMPR1A/BMPR2, and BMP8A/BMPR1A/BMPR2." (PMID 37733241, 2023). "The proposed pathway is that SMAD4’s involvement in TGF-β signalling is shared with TGFBR1/2 and FBN1, genes involved in connective tissue disorders, where SMAD4 is a transcriptional regulator and tumour suppressor." (PMID 38066625, 2023). "In tumor tissues, we found that CRC patients with positive VPS9D1-AS1 expression shown higher levels of TGF-β, TGFBR1, and SMAD1/5/9." (PMID 36458816, 2022). "Meanwhile, GDF-10 can activate the TGFBR1/Smad3/ERK pathway to promote the growth and migration of tumor cells, and further regulate the recruitment and activation of Smad family transcription factors." (PMID 36714584, 2022). "Sampling methods (i.e., tumor tissues or cell lines vs. whole ovaries): Tumor tissues and GCT cell lines have been used for the transcriptomic analyses of human GCTs, while ovaries were used for the RNA-seq analysis of TGFBR1-CA mice." (PMID 35565312, 2022). "TGFBR1, PDCD1LG2, CD274, and TNFSF14 are involved in tumor immune evasion and are effective targets for tumor immunotherapy." (PMID 36371223, 2022). "The PPI network analysis with cancer-related terms defined six proteins: TGFBR2, TGF-alpha, FGF21, SMAD4, TGFBR1, and FZD3, most of which are involved in tumor development." (PMID 35999337, 2022). "circ_0002770 exerts its tumor-promoting role by sponging miR-331-3p, which in turn promotes expression of MAPK pathway regulators dual specificity phosphatase 5 (DUSP5) and transforming growth factor beta receptor 1 (TGFBR1)." (PMID 34638331, 2021).
tumor (continued). "Most DEGs in the brown module were involved in tumor progression or metastasis (module membership >0, cor = 0.83, p < 2.2e-16), including NOTCH3, VEGFA, SNAL1, TGFBR1, and MMP14, thereby confirming the correlation of some DEGs with phenotypes." (PMID 34458146, 2021). "Considering its multiple tumor-promoting effects in various cancers, we focused on TGF-β signaling-related genes, namely TGFBR1, MAP3K8, and FURIN (red arrow)." (PMID 34537073, 2021). "We found the positive correlation between HILPDA expression and immunosuppressive genes, such as PD-L1, PD-1, TGFB1, and TGFBR1, indicates the key role of HILPDA in regulating tumor immunosuppressive microenvironment." (PMID 33816230, 2021). "The protein levels of TGFβ1 secreted from cells and expressed in tumor tissues of tumor bearing mice were both detected by ELSIA and IHC, and the expression of TGFBR1 was detected by western blot." (PMID 34249724, 2021). "RNA-seq data also demonstrated that several genes related to adoptive immune systems which have pro-tumor action, such as TGFβ2, TGFBI, TGFBR1, TGFBR3, PLAU, IL-1β, and IL-33 are higher in Pn-positive cells than Pn-negative cells." (PMID 34680221, 2021). "Moreover, TGFBR1 inhibitor could reduce the metastasis ability of tumor cells in vivo." (PMID 32582282, 2020). "In this regard, transforming growth factor beta receptor I (TGFβR-1) is overexpressed in patients with skin SCC, and the anti-tumor effects of TGFβR-1 inhibitors were proven in several types of cancer." (PMID 32392811, 2020). "For instance, Liu and colleagues showed that TGFBR-1 inhibitor and VEGF synergistically induced tumor angiogenesis through α5-integrin upregulation." (PMID 33553157, 2020). "Intriguingly, some of these molecules are related to oncogenesis and tumour progression/metastasis, namely, HRAS, KRAS, TGFBR1, TGFBR2, RB1, ITGA6, ITGB4, mTOR, TSC2 and APLP2." (PMID 30258067, 2018). "Both of these processes involve altered activation of TGFBR1, which mediates TGFB pathway signaling and has been reported to possess both oncogenic and tumor suppressive activity." (PMID 28146434, 2017). "TGFBR3 can act as a tumor suppressor, which acts negatively on TGF-β signaling by binding to TGFBR1 and TGFBR2 separately, thereby inhibiting the TGFBR1/2 complex formation." (PMID 29084941, 2017). "Taking advantage of immunocompetent Tgfbr1/Pten‐knockout HNSCC models, we observed restoration of effector T cells by targeting CD4+TIM3+ cells and CD8+TIM3+ cells and decreasing MDSCs in tumor microenvironment and peripheral environment." (PMID 28102051, 2017). "We tested eleven distinct mutations in several genes, including the oncogenes ERBB2 and VEGFR2 and the tumor suppressors CHEK2 and TGFBR1." (PMID 28743916, 2017). "To address the role of tumor-derived MMP9 in tumor vascularization, we utilized MDA-MB-231 cells expressing constitutively-active ALK5/TGFBR1-T204D (caALK5) and MDA-MB-231-caALK5 cells depleted of MMP9 by shRNA." (PMID 28423685, 2017). "It was observed an enrichment of MAPK-related genes, represented in our results by upregulation, in the tumor samples, of TGB1, TGFB2 and TGFBR1 that were shown to activate the MAPK pathway." (PMID 28490781, 2017). "Blockade of TGFBR1 signaling via the kinase inhibitor SM16, induces the accumulation at the tumor site of hypersegmented neutrophils able to directly kill tumor cells and mediate a CD8+ cell dependent immunity by the secretion of pro-inflammatory cytokines." (PMID 27618112, 2016). "We also observed thatTGFB2, TGFBR1 and SMAD2 genes had greater expressionin tumours with low MEG3 expression, further supporting our invitro cell culture results that MEG3 negatively regulates theTGF-β pathway genes." (PMID 26205790, 2015). "EGFR inhibitors, including cetuximab and lapatinab, can dramatically reduce tumor burden in HNSCC animal models or patients In the present study, the EGFR pathway is frequently activated in Tgfbr1/Pten 2cKO mice." (PMID 25723392, 2015).
tumor (continued). "Notably, CAF-FAP and CAF-C7 both showed upregulated chemokine signaling pathway, but showed high expression of pro-inflammatory genes (CCL2, CXCL12, GDF15, and LIFR) at tumor core and pro-fibrotic genes (TNFRSF12A, TGFBR1, TGFBR2) at FR, respectively." (PMID 39870619, 2025). "There was no discernible difference between the miR-320a target mRNA TGFBR1 in tumor tissue and the nearby non-tumor tissue." (PMID 40630212, 2025). "Preclinical studies suggest, that during tumor progression, key components of the canonical TGF-β pathway (e.g., SMAD2/3, SMAD4, TGFBR1/2) are often epigenetically downregulated via histone modifications, potentially leading to non-canonical pathway activation with pro-tumorigenic signaling routes." (PMID 40488800, 2025). "The median ΔCt value of TGFBR1 in tumor tissue was -7.5 (IQR ±4.45), in non-tumor tissue -6.25 (IQR ±8.23), fold change 1.42 (IQR ±9,68), 0.70 times downregulation and p = 0.126." (PMID 40630212, 2025). "Additionally, older patients with a tumor exhibited elevated FUT2, FUT3, and FUT8 coexpression with tumor-promoting IL6ST, IL22RA1, TGFB1, and TGFBR1 genes compared with young tumor." (PMID 38456503, 2024). "Additionally, a differential expression of the cytokine genes CCL2, CCL20, TGFB1, and TGFB2; the transcription factor gene IRF4; and the receptor genes CCR2, IL10RB, TGFBR1, and TGFBR2 was identified in tumor tissue and vestibular nerve tissue." (PMID 39272860, 2024). "Then, TGFβ1 binds to TGFBR1/R2 in tumor cells to activate Smad2/3 signalling to increase the expression of PAI-1, which further activates PI3K/AKTThr308, p-Bad and Bcl-2 to support tumor cell survival in circulation." (PMID 37705745, 2023). "Guided by the RNA-seq finding, we revealed ovarian WNT signaling activation in TGFBR1-CA mice by demonstrating the localization of non-phosphorylated active CTNNB1 to the tumor foci." (PMID 35565312, 2022). "Besides, ADORA2A-AS1 promoted the expression of transforming growth factor-beta receptor 1 (TGFBR1) and ATP binding cassette subfamily C member 2 (ABCC2) via sponging miR-665, thereby exerting a tumor-promoting activity." (PMID 35034552, 2022). "Non-phospho CTNNB1 (i.e., active CTNNB1) was detected in tumor tissues of TGFBR1-CA ovaries, whereas its expression was restricted to early stage follicles in the control ovaries." (PMID 35565312, 2022). "Moreover, depletion of KRT80 attenuated xenograft tumor growth and the expressions of KRT80, Ki-67, and TGFBR1." (PMID 36248424, 2022). "Moreover, the positive correlation between FOXD1 expression and immunosuppressive genes, such as PD-L1, IL-10, TGFB1 and TGFBR1, indicate the key role of FOXD1 in regulating tumor immunology." (PMID 34028536, 2021). "Here, we use the MMTV-PyMT model to identify two subgroups of CSCs and show that transforming growth factor β (TGFβ) receptor 1 (TGFBR1)/ALK5 inhibition prevents metastasis but not tumor initiation." (PMID 31257133, 2019). "Finally, tumor induction by 7,12-dimethylbenz(a)anthracene in conditional TGF-β receptor 1 (Tgfbr1) knockout mice is mediated through the activation of AKT pathway." (PMID 31886179, 2019). "Moreover, deletion of Tgfbr1 and Pten in murine epithelia activated HIF-1α, CD73 and subsequently induced A2AR overexpression in tumor infiltrating immune cells, accumulating immunosuppressive CD4+ Foxp3+ Tregs in the stroma of tumors." (PMID 28592285, 2017). "The observation that overactivation of TGFBR1 using Gdf9-iCre did not increase oocyte apoptosis suggests that the reduction of follicle/oocyte numbers in TGFBR1-CAG9Cre mice may be associated with the disruptive effect (e.g., impairment/destruction) of tumor formation and development." (PMID 29221447, 2017). "In addition, haploinsufficiency of Tgfbr1 reduces the development of Kirsten rat sarcoma viral oncogene homolog (KRAS)-driven pancreatic precancer formation, uncovering a potential tumor promoting effect of TGFβ signaling." (PMID 27344183, 2016).